MELTF-AS1 (MELTF antisense RNA 1)
Synonyms: AC068302.3; PLANE; MFI2-AS1
Gene: Long non-coding RNA gene on chromosome 3 (196,999,460 to 197,004,748, forward strand). Ensembl gene ENSG00000228109.
Diseases named in the same sentence as MELTF-AS1 in open-access papers:
MELTF-AS1 is named in the same sentence as 9 diseases in open-access papers, as found by Europe PMC text mining. Sharing a sentence is not in itself a finding about the gene and the disease. The quoted sentences say what the papers report.
osteosarcoma (1 paper, 2021). A usually aggressive malignant bone-forming mesenchymal neoplasm, predominantly affecting adolescents and young adults. "After silencing RREB1, the expression level of MELTF-AS1 in osteosarcoma cells was significantly reduced, and after overexpression of RREB1, the expression level of MELTF-AS1 increased significantly." (PMID 34729248, 2021).
MELTF-AS1 also shares sentences with these, for which no sentence is quoted: cancer (3 papers); esophageal squamous cell carcinoma (2); colon adenocarcinoma (1); colon adenoma (1); hepatocellular carcinoma (1); lung squamous cell carcinoma (1); non-small cell lung carcinoma (1); tumour (1).